TNFAIP6 (TNF alpha induced protein 6)
Diseases named in the same sentence as TNFAIP6 in open-access papers (continued):
Sharing a sentence is not in itself a finding about the gene and the disease.
cancer (33 papers, 2008 to 2025). A tumor composed of atypical neoplastic, often pleomorphic cells that invade other tissues. "A recent pan-cancer meta-analysis showed TNFAIP6 signalling positively correlated with neutrophil infiltration, and was an adverse prognostic factor in multiple cancers." (PMID 40792276, 2025). "The TNFAIP6 protein was significantly overexpressed in cancer tissue compared to normal pulmonary tissue, according to the IHC examination." (PMID 38204755, 2023). "Correlation analysis also shows that the following histaminergic transcripts: GNA15, HRH2, MAOA, WASF2, and those related to inflammation: AEBP1, CXCL1, 2, 3, and 8, SPHK1, and TNFAIP6 play an important role in cancer tissue." (PMID 36902343, 2023). "For the quantification of PD-L1 expression (biomarker in cancer immunotherapy), CCL18, TNFAIP6, and BCL2A1 had higher diagnostic efficiency (AUC > 0.7)." (PMID 35265629, 2021). "FCRs with risk alleles at the second locus demonstrate increased expression of TNFAIP6, which correlates with poor prognosis in multiple human cancers." (PMID 33983928, 2021). "Conversely, TNFAIP6 has been reported to enhance glucose uptake and promote glycolysis in cancer cells, though its prognostic relevance in HCC remains unclear and warrants further investigation." (PMID 41228357, 2025). "TNFAIP6 is involved in cell-cell and cell-matrix interactions in inflammation and cancer, and its increased expression in t-PAPS may be explained by the inflammatory process of the disease." (PMID 37035297, 2023). "Importantly, increased TNFAIP6 expression is correlated with reduced survival for several cancers, and it is upregulated in two lymphoma tumor types in humans." (PMID 33983928, 2021). "Furthermore, we detected the effects of TNFAIP6 on cancer cell viability by CCK8 assays." (PMID 38204755, 2023). "Moreover, TNFAIP6 also promotes invasion in various other cancers." (PMID 37511403, 2023). "Whether TNFAIP6 directly affects cancer cell proliferation also needs further validation." (PMID 38204755, 2023). "TNFAIP6 has been also joined in extracellular matrix (ECM) remodeling, cell adhesion, and migration to regulate cancer progression." (PMID 38376551, 2024). "After taking the intersection, we found that TNFAIP6 and TLR6 were not only overexpressed in cancer tissue but also indicated poorer prognosis." (PMID 38204755, 2023). "Taking into consideration the cancer development process, the following histaminergic genes stood out: GNA15, HRH1-HRH4, MAOA, WASF2, along with inflammation-related genes: AEBP1, CXCL1, CXCL2, CXCL3, CXCL8, SPHK1, and TNFAIP6." (PMID 36902343, 2023). "Similarly, testis-restricted targets such as SPA17, TEX14, LAMA1, SMOC1, TNFAIP6, GPC2, and COL20A1 may also be leveraged for their cancer-specificity." (PMID 38702309, 2024). "Here we found that TNFAIP6 expression is not positively related to the malignant tumor grade." (PMID 35578123, 2022).
infection (17 papers, 2012 to 2025). The state of being infected such as from the introduction of a foreign agent such as serum, vaccine, antigenic substance or organism. "The differentially expressed cytokines such as IL6, IL10, IL11, IL15, TNFSF10, TNFRSF6B and TNFAIP6 were detected in the lung of goats after Pm infection in this study." (PMID 35739866, 2022). "TNFAIP6-RNAi (54322–1) had the best infection efficiency and showed a 72% interference rate." (PMID 36468025, 2022). "An exception to this trend was regulation of SERPINB2 and TNFAIP6, which showed similar upregulation regardless of infection mode." (PMID 34925266, 2021). "Looking at the cytokine levels, there was observed up regulation of pro-inflammatory TNF-α induced proteins (TNFAIP6 [log2FC 2.6], TNFAIP8 [log2FC 5.3]) involved in systemic inflammation; and also, elevation of interleukins IL21 (Log2FC 3.7) and IL1 receptor (Log2FC 2.0) that respond to infection." (PMID 32000760, 2020).
bacterial infection (3 papers, 2008 to 2025). "In particular, we identified that FFAR2+TNFAIP6+ NEUs and THBS1+IL1B+ MOs undertook an important role in the immune response to bacterial infection." (PMID 36119025, 2022). "Considering the CSF cell compositions, the CSF in the refractory stage contained fewer FFAR2+TNFAIP6+ NEUs and THBS1+IL1B+ MOs, which indicated that an immune response to a bacterial infection was not the main reaction to this condition." (PMID 36119025, 2022).
Cardiovascular Disease (2 papers, 2023 to 2025). "Interestingly, IPA determined that TNFAIP6 is a molecule involved in the Carbohydrate Metabolism as well as Cardiovascular Disease networks." (PMID 40868918, 2025).
adenocarcinoma (1 paper, 2023). A common cancer characterized by the presence of malignant glandular cells. "Significant upregulation of TNFAIP6 and TLR6 and downregulation of P2RY13 and CYP27A1 were observed in all three adenocarcinoma cell lines." (PMID 38204755, 2023).
TNFAIP6 also shares sentences with these, for which no sentence is quoted: myocardial infarction (27 papers); osteoarthritis (15); injury (10); Stroke (10); diabetes (7); acute lung injury (6); ischemia (6); atherosclerosis (5); ischemic stroke (5); alcoholic hepatitis (4); bronchopulmonary dysplasia (4); inflammation (4); neurodegenerative disease (4); abortion (3); acute myocardial infarction (3); coronary artery disease (3); influenza (3); subarachnoid hemorrhage (3); systemic lupus erythematosus (3); type 1 diabetes (3); brain infarct (2); dry eye (2); endotoxemia (2); glomerulonephritis (2); Hepatic steatosis (2); immune diseases (2); infarct (2); intracerebral hemorrhage (2); liver disease (2); liver fibrosis (2).
A further 88 diseases each share a sentence with TNFAIP6 in 2 papers or fewer.